INS (insulin)
Diseases named in the same sentence as INS in open-access papers (continued):
Sharing a sentence is not in itself a finding about the gene and the disease.
Hypoglycemia (continued). "The effects of insulin are opposed by glucagon that drives mobilization and oxidation of metabolic stores during fasting or hypoglycemia." (PMID 37066881, 2023). "Like insulin, metformin has also stood the test of time for over six decades, while the SUs have slowly lost favor in the last two decades due to side effects of hypoglycemia and weight gain." (PMID 36845885, 2023). "About 4% of patients with T1DM who use basal-bolus insulin regimens experience hospitalization for severe hypoglycemia." (PMID 35858952, 2022). "RT2;B6 mice develop functional PanNETs characterized by tumor insulin secretion, hypoglycemia, and premature mortality but rare metastases." (PMID 35118189, 2022). "In turn, hypoglycemia induced by administering insulin intravenously leads to activation within the hypothalamus, cerebral hemisphere, striatum, and caudate nucleus, thereby contributing to increased appetite." (PMID 35743630, 2022). "During fasting or hypoglycemia, several counterregulatory hormones are secreted, whereas a decrease in plasma insulin concentrations is observed." (PMID 35742928, 2022). "Classically, hepatic glycogenosis occurred in patients using excess rapid insulin, which resulted in hypoglycemia, which was corrected by glucose intake, resulting in a vicious circle of hepatic glycogen accumulation." (PMID 35655318, 2022). "Insulin is also a key regulator for brain glucose metabolism, and hypoglycaemia can lead to a migraine attack in migraine patients after prolonged fasting." (PMID 35627115, 2022). "Nocturnal hypoglycemia (NH) is a dangerous complication of insulin therapy that often goes undetected." (PMID 36013211, 2022). "Concerns about the side effects of insulin, such as hypoglycaemia, need to be elicited and addressed by health care providers during each review." (PMID 35172774, 2022). "Emergency carbohydrates can be consumed if hypoglycemia cannot be avoided by decreasing insulin delivery or increasing glucagon." (PMID 36411933, 2022). "Patients have to face multiple challenges due to the complexities of insulin therapy and the variability in glucose levels from multiple factors, like meals, exercise, illness, and antecedent hypoglycemia." (PMID 35498423, 2022). "In Ishikawa cells, insulin stimulation causes PHLPP1 and PHLPP2 to increase in hypoglycemia conditions and this effect is enhanced by PTC-209 treatment." (PMID 36497428, 2022). "For example, when insulin levels are low, it is recommended that an individual should consume 30-60g of carbohydrate per hour to prevent hypoglycaemia during exercise." (PMID 36246914, 2022). "Both GLP-1 and GIP can stimulate pancreatic beta cells to secrete insulin in a glucose-dependent manner to control blood glucose levels with hypoglycemia occurring very rarely as an adverse effect." (PMID 35252271, 2022). "As shown, when using the iZMPC (blue lines) the system presents hypoglycemia episodes because of the delivery of insulin doses higher than the required for the situation of the subject (see that at 7:00h, the variations in the subject induce hypoglycemia)." (PMID 35265035, 2022). "Hypoglycemia is a common adverse effect in patients with DM who are mainly treated with insulin and insulin secretagogues." (PMID 35057487, 2022). "Adverse events occurred in one patient in the control group; the patient reported a hypoglycemia symptom owing to maladjusted diet and insulin concentration." (PMID 36233755, 2022). "Secondary endpoints included: HbA1c < 53.0 mmol/mol attainment, weight change, treatment‐emergent hypoglycemia, end‐of‐treatment insulin dose, and safety." (PMID 35762390, 2022). "At least one episode of hypoglycemia occurred in all Gymnema patients, prompting insulin dosage reductions." (PMID 35268815, 2022). "Ideally women should be advised to perform blood glucose monitoring and individual insulin adjustment and how to manage hypoglycaemia already in the pregnancy planning period." (PMID 36432552, 2022).
Hypoglycemia (continued). "Mice lacking Vglut2 in the VMHSF1 neurons results in a lower fasting glucose, and impairs CRR to insulin-induced hypoglycemia and 2-DG-induced glucopenia." (PMID 35619170, 2022). "During hypoglycemia, glucose is oxidized to gluconic acid while the local pH is below pKa, leading to the ultimate disassembly of the hydrogel and the release of insulin." (PMID 35215689, 2022). "Even mild to moderate exercises can increase insulin sensitivity for the following 11 to 16 h and, in combination with metabolic counter-regulatory mechanisms, lead to late-onset or nocturnal hypoglycemia." (PMID 36231598, 2022). "The authors of that study noted that while the lower ratio (2 g dextrose for every 1 unit of insulin) resulted in a more substantial decrease in [K+], it also led to greater occurrences of hypoglycemia than the higher dextrose:insulin ratio." (PMID 36350735, 2022). "Investigation proceeded to a 72 hour fast with repeat measurements confirming appropriate suppression of serum insulin and c-peptide in the setting of a symptomatic hypoglycemia of 1.9 mmol/L." (PMID 36303203, 2022). "During a shortage of natural insulin, it is necessary to inject glargine analog in fusion with an analog having long action taken with food to decrease post-prandial hypoglycemia." (PMID 35723344, 2022). "The improved insulin analogs (i.e., the premixed insulin analogs) remarkably declined the possibilities of hypoglycemia, particularly nocturnal evidence, gaining weight, and other adverse effects." (PMID 35723344, 2022). "For patients using an MDI regimen, adjustment of meal bolus insulin should be considered for exercise performed within 3 hours of meal ingestion to prevent hypoglycemia." (PMID 35345701, 2022). "In the insulin group, women were 42% (n = 21) more likely to report having experienced hypoglycaemia at least once (p = 0.041)." (PMID 35482748, 2022). "Changes in BMI-1 expression are correlated with changes in AKT phosphorylation but decreased expression of BMI-1 during prolonged insulin stimulation is accompanied by increased expression in PTEN only in hypoglycemia conditions." (PMID 36497428, 2022). "Insulin-induced hypoglycemia activates widespread 5-HT release in several forebrain areas, such as the ventromedial hypothalamus, perifornical hypothalamus, paraventricular hypothalamus, cerebral cortex, and paraventricular thalamic nucleus." (PMID 35910256, 2022). "Insulin-induced hypoglycemia (2mmol/l: 36mg/dl) was induced and blood sampling performed at baseline and hypoglycemia." (PMID 36017315, 2022). "If a treatment for T1D can restore normal insulin release into the portal vein, glucose regulation and hypoglycemia prevention will certainly become easier during rest and activities." (PMID 36992764, 2022). "We have highlighted the guidelines that are widely practiced along with the common obstacles like hypoglycemia which can be overcome by timely measurements of blood glucose and appropriate modifications of the insulin dose." (PMID 35959169, 2022). "Factitious hypoglycaemia is defined by an intentional insulin use or ingestion of oral hypoglycaemic agents to induce self‐harm, seek attention and gain care." (PMID 36117266, 2022). "It has been reported that NO production in the VMH is indispensable for glucose-sensing in GI neurons, as well as CRR to insulin-induced hypoglycemia." (PMID 35619170, 2022). "Concerns about the risks of hypoglycemia can prevent or delay the intensification and titration of insulin." (PMID 36149907, 2022). "The simultaneous AA-induced increase in plasma glucagon levels and insulin levels allows both insulin-induced energy-consuming processes to coincide with the processes of glycogenolysis or gluconeogenesis to prevent hypoglycemia." (PMID 35448534, 2022). "In summary, our screening study does show clear promise in aiding in forensic death investigations in relation to the diagnosis of potential hypoglycemia- and insulin-intoxication-related deaths." (PMID 36676928, 2022).
Hypoglycemia (continued). "PLGS technology predicts glucose concentration trends, then suspends insulin delivery before hypoglycemia occurs." (PMID 36099285, 2022). "Nocturnal hypoglycemia the night following ACT occurred mostly in people who administrated an additional insulin bolus before midnight (3 out of 5 participants with nocturnal hypoglycemia)." (PMID 36237197, 2022). "Taking insulin therapy for a longer time is 4.31 times more likely to practice prevention of hypoglycemia more than taking insulin with less time (AOR = 4.31,95%CI:2.60,6.02)." (PMID 36318542, 2022). "C-peptide is often used to distinguish insulin produced by the body from injected insulin to estimate ISR, to determine insulin resistance, and to indicate a differential diagnosis of fasting hypoglycemia with hyperinsulinism." (PMID 35991187, 2022). "The parents try to monitor blood glucose fluctuations and make adjustments of insulin doses with primary aim of avoiding hypoglycaemia." (PMID 35399686, 2022). "Pharmacological or genetic inhibition of ACC1 resulted in impaired glucagon secretion at low glucose and in response to fasting or insulin-induced hypoglycaemia in vivo." (PMID 35304577, 2022). "The implementation of threshold systems designed to suspend insulin delivery for up to 2 hours until CGM glucose is at a low threshold have displayed promising results in reducing nocturnal hypoglycemia." (PMID 35336018, 2022). "One forum user used massage for sore muscles and ended up having unexpected hypoglycaemia, and another forum user used chiropractic and noticed a reduction in his insulin needs." (PMID 36136208, 2022). "When the blood insulin levels are high, myocytes and/or leptocytes control these transporters, inducing hypoglycemia." (PMID 36552690, 2022). "The emergency treatment of hyperkalaemia includes shifting potassium into cells using intravenous insulin, with dextrose added before, with or after insulin administration to prevent hypoglycaemia." (PMID 35552566, 2022). "This real-world prospective study aims to assess the impact of hypoglycemia on productivity and utility in insulin-treated adults with T2DM from Ontario and Quebec, Canada." (PMID 35343912, 2022). "Insulin induced the same level of hypoglycemia in Agpat5flox/flox and AgRPAgpat5KO mice of both sexes." (PMID 36180454, 2022). "We compared the effect of sacubitril/valsartan, relative to valsartan, on HbA1c, new insulin therapy and hypoglycemia in the randomized controlled trial PARAGON-HF, and performed pooled analyses of PARAGON-HF and PARADIGM-HF." (PMID 35717169, 2022). "Of the cats that received insulin and dextrose, three presented hypoglycemic and were subsequently excluded from analysis regarding the development of hypoglycemia." (PMID 36350735, 2022). "During hypoglycemia, the pancreas decreases the secretion of insulin and increases the secretion of glucagon." (PMID 36687427, 2022). "Late insulin initiation and slow titration are likely due at least in part to the fear of hypoglycemia and weight gain." (PMID 35864262, 2022). "A positive response to glucagon stimulation at the time of hypoglycaemia is indicative of insulin-mediated hypoglycaemia." (PMID 36440205, 2022). "Cord blood C-peptide, which is secreted in equimolar levels with insulin, represents the insulin-secretory activity in the fetus, and fetal hyperinsulinemia or hypoglycemia is characterized by higher levels of cord C-peptide." (PMID 36685522, 2022). "The abnormal release of glucagon appears to be specific to hypoglycemia, however, since other conditions (like giving amino acids or withdrawing insulin and even physical activity itself) result in normal elevations of this hormone." (PMID 36992764, 2022). "PLGS systems use algorithms that can predict the occurrence of hypoglycemia and pre-emptively suspend insulin delivery." (PMID 36011925, 2022).
Hypoglycemia (continued). "Factitious hypoglycemia (FH) is the deliberate use of insulin preparations or oral hypoglycemic drugs with the aim of lowering blood glucose levels into the pathologically-hypoglycemic range." (PMID 36376919, 2022). "Specifically, when 3 algorithms were used to prompt insulin pump suspension, nocturnal hypoglycemia was avoided, with a sensitivity of 60%." (PMID 35862181, 2022). "Thus, people living with T1D require life-long insulin replacement therapy with the goal of maintaining glucose levels close to normal while minimizing the risk of iatrogenic (i.e. complication induced by the treatment) hypoglycemia (blood glucose [BG] < 3.9 mmol/L)." (PMID 36237197, 2022). "Having this protocol ordered automatically for all patients on insulin improves patient safety as it eliminates the time consuming task for the nurse to contact the provider and await orders to treat hypoglycemia." (PMID 35917098, 2022). "Mice from the three genotypes had the same body weight, the same basal glycemia and insulin-induced hypoglycemia." (PMID 36180454, 2022). "Tight glucose control is guided by our previously developed and validated computerized LOGIC-Insulin algorithm that has shown to be superior to nurse-guided glucose control, with virtually prevention of hypoglycemia." (PMID 36123593, 2022). "The subjects underwent insulin-induced hypoglycemia (2 mmol/L; 36 mg/dL); blood samples were drawn at baseline, upon the induction of hypoglycemia, and 4 h and 24 h post-hypoglycemia, with a quantitative polymerase chain reaction analysis of miRNA undertaken." (PMID 36499023, 2022). "Transfersomes have been reported to be effective for the transdermal delivery of insulin, inducing hypoglycemia in healthy human volunteers." (PMID 35890174, 2022). "Patients not responsive to octreotide and diazoxide require surgical resection of the pancreas, physically removing ~ 95% of insulin-secreting cells to attenuate their severe hypoglycemia." (PMID 36202918, 2022). "Statistically notable variation in hypoglycemia between human and animal insulin also seems comparable." (PMID 36381916, 2022). "The oral administration of CaCO3-HA NCs resulted in hypoglycemia in a controlled-release manner as compared to subcutaneously administered insulin." (PMID 35890301, 2022). "Insulin-induced hypoglycaemia dramatically prolongs the duration of CSD in experimental mice, which is thought to induce migraine aura and lead to headaches." (PMID 35627115, 2022). "Further studies are required to expand on the potential of postmortem metabolomics as a tool in hypoglycemia-related death investigations, and the future application of screening for potential insulin intoxications." (PMID 36676928, 2022). "In 1963, 40 years after the discovery of insulin, Kadish invented an insulin pump delivering insulin and glucagon (to prevent hypoglycemia)." (PMID 35062598, 2022). "Findings were similar for hypoglycemia rates per week, with rates approximately two and five times higher with SU and insulin than metformin after adjustment for HbA1c." (PMID 35450869, 2022). "Previous data have implicated alcohol in up to one-fifth of hospital admissions due to hypoglycemia in individuals treated with insulin." (PMID 36191264, 2022). "This is supported by findings by others showing that decreased islet size is accompanied by shrunken β-cells with crowding of β-cell nuclei, following 10 days of continuous insulin-induced hypoglycaemia in mice." (PMID 35982111, 2022). "Parameters that included BG within range of 70-180 mg/dL, insulin treatment regimen and frequency of hypoglycemia were evaluated." (PMID 35758838, 2022). "Taking insulin therapy for a longer time is 4.31 times more likely to practice prevention of hypoglycemia more than taking insulin with less time." (PMID 36318542, 2022). "Use of insulin delivery systems also helps to reduce hypoglycemia and consequently its complications." (PMID 35831938, 2022).
Hypoglycemia (continued). "One dog was diagnosed based on clinical signs consistent with neuroglycopenia, combined with an inappropriate fasting insulin level in the presence of hypoglycaemia." (PMID 35079406, 2022). "In participants treated with CSII, only one reported using temporary insulin basal rate reduction (BRR) as a mitigation strategy for nocturnal hypoglycemia which consisted of a 50% BRR for 4-hours." (PMID 36237197, 2022). "The reasons of poor glycemic control in patients on premix insulin include fear of weight gain and hypoglycemia and the need for frequent self-monitoring of blood glucose." (PMID 35222287, 2022). "Insulin treatment significantly increased pyroptosis in the hypoglycemia groups compared with the DM group (p < 0.05), and pyroptosis activity was higher with RH-DM than with H-DM (DM 2.54-, H-DM 3.08-, and RH-DM 4.04-fold compared with control)." (PMID 35915611, 2022). "If there is nocturnal hypoglycemia, the dose of insulin needs to be reduced; otherwise, the dose of insulin needs to be increased." (PMID 36237834, 2022). "Severe postprandial hypoglycemia following an exaggerated insulin response to meals has been recognized as a consequence of these procedures." (PMID 35399928, 2022). "In most cases, blood glucose was well controlled by precise insulin administration, but hypoglycemia and complications are inevitable in some patients." (PMID 35242127, 2022). "Forty-three primary studies reported the duration of monitoring for hypoglycaemia, of which half monitored up to six hours following the administration of insulin therapy." (PMID 35552566, 2022). "Its absence enhances insulin signaling leading to hypoglycemia, a dangerous complication found after insulin overdose." (PMID 35406129, 2022). "In the present study, we showed sustained β-cell adaption in response to prolonged continuous hypoglycaemia induced by insulin-infusion over eight weeks and a gradual return to normoglycaemia subsequent to infusion-stop." (PMID 35982111, 2022). "The α cells of the pancreatic islets secrete glucagon to raise blood glucose in response to hypoglycemia, and the δ cells secrete somatostatin to inhibit the secretion of both insulin and glucagon." (PMID 35669692, 2022). "This is further illustrated by the rapid transition from reductions in insulin secretion during acute hypoglycaemia to an increase following a return of glucose supply." (PMID 35982111, 2022). "CRN02481 prevented fasting hypoglycaemia and amino acid-stimulated insulin secretion in a Sur1-/- mouse model of CHI." (PMID 36237195, 2022). "INS-PEG-LMWP resulted in sustained hypoglycemia with a relative bioavailability of 26.86% as compared to the insulin solution." (PMID 35890301, 2022). "Hypoglycemia is a fairly common complication in diabetic patients, particularly in those on insulin therapy." (PMID 35858952, 2022). "WTD contains a high percentage of sucrose (35%), and sucrose rapidly increases blood glucose levels, leading to insulin release and hypoglycemia." (PMID 35782606, 2022). "In those cases, to avoid hypoglycemia, for patients in continuous subcutaneous insulin infusion (CSII), the basal rate was decreased or suppressed." (PMID 35813646, 2022). "Gla‐300 switchers had significantly lower inpatient/ED‐associated hypoglycaemia incidences than Gla‐100/IDet switchers in subgroups 1 (uncontrolled HbA1c), 2 (prandial insulin), 4 (recent hypoglycaemia), and 7 (sulphonylurea use)." (PMID 34807513, 2022). "The diagnosis of an insulinoma requires the demonstration of the simultaneous occurrence of hypoglycaemia and blood insulin levels that are within or above the high end of the reference interval." (PMID 36288153, 2022). "Firstly, most prior studies were conducted during hospitalization, and they focused merely on the insulin-used population with poor glucose control to investigate the incidence of hypoglycemia." (PMID 36443872, 2022).